LINC02587 (long independently transcribed non-coding RNA 2587)
Synonyms: MEOX2-AS1
Gene: Long non-coding RNA gene on chromosome 7 (15,688,186 to 15,725,306, forward strand). Ensembl gene ENSG00000229108.
Diseases named in the same sentence as LINC02587 in open-access papers:
LINC02587 is named in the same sentence as 4 diseases in open-access papers, as found by Europe PMC text mining. Sharing a sentence is not in itself a finding about the gene and the disease. The quoted sentences say what the papers report.
breast carcinoma (1 paper, 2023). "High LINC02587 (also called MEOX2-AS1) expression has previously been seen in breast cancer and colon adenocarcinoma." (PMID 37848823, 2023).
glioma (1 paper, 2023). A benign or malignant brain and spinal cord tumor that arises from glial cells (astrocytes, oligodendrocytes, ependymal cells). "In this view, this study aimed to examine whether LINC02587 serves as a functional regulator in gliomas." (PMID 37848823, 2023).
tumor (1 paper, 2023). "The analyses of GEPIA databases revealed that LINC02587 is significantly correlated with a variety of tumor sites;LINC02587 is located on 7p21.2 and contains some CpG islands." (PMID 37848823, 2023).
LINC02587 also shares sentences with these, for which no sentence is quoted: colon adenocarcinoma (1 paper).